C12orf43 (chromosome 12 open reading frame 43)
Description:
Plays a role in the regulation of Wnt signaling pathway during early development.
Synonyms: CUSTOS; FLJ12448
Tractability: No criterion of Open Targets' tractability assessment is met for any kind of drug.
Gene: Protein-coding gene on chromosome 12 (121,000,486 to 121,016,504, reverse strand). Ensembl gene ENSG00000157895.
Subcellular location: Nucleus envelope
Subcellular location (Human Protein Atlas): Nucleoli; Golgi apparatus
Gene Ontology:
Molecular function: protein binding
Biological process: negative regulation of Wnt signaling pathway; Spemann organizer formation; Wnt signaling pathway
Cellular component: nucleolus; nuclear envelope
Genetic constraint (gnomAD): Loss-of-function variants: 14 observed, 18.51 expected, observed/expected ratio (o/e) 0.76, 90% interval 0.5 to 1.18. The upper end of that interval is the gene's LOEUF score, 1.18, which puts it in group 5 of 6, group 1 being the genes least tolerant of losing a copy. Missense variants: 332 observed, 339.11 expected, observed/expected ratio (o/e) 0.98, 90% interval 0.89 to 1.07. Synonymous variants: 144 observed, 129.82 expected, observed/expected ratio (o/e) 1.11, 90% interval 0.97 to 1.27.
Homologues: Orthologues: chimpanzee C12H12orf43 (100% identical), macaque C11H12orf43 (92% identical), pig C12orf43 (74% identical), guinea pig C12orf43 (70% identical), rabbit C12orf43 (66% identical), mouse 2210016L21Rik (66% identical), dog C12orf43 (64% identical), rat C12h12orf43 (64% identical), tropical clawed frog c1h12orf43 (32% identical), zebrafish zgc:162025 (30% identical).
Diseases named in the same sentence as C12orf43 in open-access papers:
C12orf43 is named in the same sentence as 5 diseases in open-access papers, as found by Europe PMC text mining. Sharing a sentence is not in itself a finding about the gene and the disease. The quoted sentences say what the papers report.
diabetes (1 paper, 2023). "Interestingly, C12orf43, TBL1X and TNKS were significantly associated with diabetes or hypertension-related phenotypes in the UK Biobank." (PMID 37239390, 2023).
cardiovascular disease (1 paper, 2019). "Consistent with other studies, there are 19 SNPs within a 43 Kb span on chr 12 encompassing the HNF1A gene, a hepatic transcription factor which has been repeatedly found to affect CRP expression, as well as C12orf43, variants of which have been linked to cardiovascular disease and CRP expression." (PMID 31622379, 2019).
C12orf43 also shares sentences with these, for which no sentence is quoted: asthma (1 paper); Hypertension (1); infection (1).